HMGB1 (high mobility group box 1)
Diseases named in the same sentence as HMGB1 in open-access papers (continued):
Sharing a sentence is not in itself a finding about the gene and the disease.
tumor (continued). "Tumor cells treated with chemotherapy or radiotherapy can express “danger” and “eat-me” signals on the cell surface (e.g., NKG2D ligands, CRT) or can release immunostimulatory factors (e.g., HMGB1) to stimulate immune effectors." (PMID 32161598, 2020). "We found that less HMGB1 proteins were present in tumor and non-tumor tissue of the Atg7ΔHep liver, as compared with the Atg7 F/F liver." (PMID 32382012, 2020). "The involvement of HMGB1/RAGE in particular, as well as HMGB1/TLR interactions, in tumor progression in both the clinical and experimental settings is now well recognized, and may involve distinct signaling pathways in different types of malignancies." (PMID 32664328, 2020). "HMGB1 and HMGB2 proteins are currently under investigation due to their involvement in DNA replication, transcription, recombination, repair, inflammation, tumor development, and cell signaling." (PMID 33076532, 2020). "In the dying tumor cell, ICD is preceded by the translocation of calreticulin, an endoplasmic reticulum stress response protein, to the plasma membrane and the extracellular release of ATP and the high-mobility group box-1 (HMGB1) protein." (PMID 32781554, 2020). "There is a strong correlation between levels of HMGB1 evaluated by Western blot analysis and the clinical and pathological features of HCC, including correlations with serum alpha-fetoprotein (AFP) levels and tumor size." (PMID 32664328, 2020). "Consistent with the database results, TNBC expressed increased levels of HMGB1, and the expression levels of HMGB1 were not correlated with tumor stage or lymph node metastasis." (PMID 32943604, 2020). "Furthermore, different interventions were administered to the tumor metastasis model, including inhibiting HMGB1 secretion from the cytoplasm, inhibiting the function of the HMG box of HMGB1, inhibiting the activation of TLR2, or clearance of the formed NETs." (PMID 32943604, 2020). "Consolidation of the NACT-induced HMGB1 during CRT seemed to be required for a favorable DMFS, which led us to investigate how tumor-defeating immune activity might have been maintained." (PMID 31893287, 2020). "Thus, HMGB1 is likely to play an important role in the development of GVHD, known as the graft-versus-tumor (GVT) effect, and possibly engraftment because of its central role in the activation of APCs and tissue regeneration." (PMID 32660524, 2020). "Furthermore, this group identified the relationship between HMGB1 and TLR4, in which HMGB1 plays an important role in the activation of DCs through TLR4 for efficient presentation of tumor antigens from dying cells." (PMID 33299138, 2020). "In our case, this might be explained by the fact that the NB-PDT treated tumor supernatants present TLR4 agonist activity, in agreement with the increase of HSP70 and HMGB1 that are TLR4 agonists themselves and can trigger IL-10 release." (PMID 32326519, 2020). "HMGB1‐modulated HIF‐1α signaling pathway can promote angiogenesis and tumor migration." (PMID 32436353, 2020). "The extracellular release of the high-mobility group box-1 (HMGB1) protein by the dying tumor cells, which facilitates cross-presentation of shed tumor antigens by dendritic cells to activate tumor-specific cytotoxic T cells, is an integral mechanism of the oxaliplatin-induced ICD." (PMID 31893287, 2020). "Murine models depict tumor antigen-specific T-cell responses when radiation-induced tumor cell death released HMGB1, which not only augmented the engulfment of antigenic materials by DCs via TRL4 but also mediated cross-presentation of tumor antigens into CD4 and CD8 T-cells." (PMID 32340275, 2020). "And we found that HMGB1, GPX4 and p-p65 were expressed in the tumor tissues." (PMID 32514250, 2020). "Moreover, knockout of either Anxa1 or Hmgb1 in MCA205 and TC1 cell abolished the tumor-growth reducing effect of the combination therapy with CDDP plus (R)-crizotinib." (PMID 30940805, 2019).
tumor (continued). "We further proved that ß-lap induced ICD and activated innate sensing via an HMGB1/TLR4 pathway and upregulated the type I IFNs signaling in the tumor microenvironment, resulting in the promotion of Batf3 DCs to cross-prime T cells and activate of antitumoral adaptive immune response." (PMID 31324798, 2019). "The release/exposure of DAMPs (calreticulin, HMGB1, ATP, IFN) by cancer cells dying after PDT stimulates the presentation of tumour antigens by dendritic cells and polarizes T cell response towards the production of IFN-γ, which are essential for anti-tumour immune responses." (PMID 31906092, 2019). "β-Lapachone-induced high mobility group box 1 (HMGB1) release activates the host TLR4/MyD88/type I interferon pathway and Batf3 dendritic cell-dependent cross-priming to bridge innate and adaptive immune responses against the tumor." (PMID 31324798, 2019). "This was associated with the activation of endoplasmic reticulum stress and tumor cell death with features of immunogenic cell death (ICD), including phosphorylation of eIF2α, increased cell surface calreticulin levels, and release of HMGB1 and ATP." (PMID 31641103, 2019). "HMGB1 binds with TLR, activating myeloid differentiation primary response gene 88 (MyD88), and finally activates NF-kB, which promotes the proliferation, invasion, and metastasis of tumor cells." (PMID 30962261, 2019). "High mobility group box 1 (HMGB1) was expressed on HCC-derived exosomal membranes and bound with high affinity to Toll like receptor-2 (TLR-2), TLR-4, TLR-9 and advanced glycation end products (RAGE), which led to tumor cell survival, expansion and metastasis." (PMID 30897788, 2019). "We found that HMGB1, secreted from tumor cells treated with DOC-based chemotherapy, did not influence the presence of suppressive myeloid (CD33+/CD11b+ MDSC) or Foxp3+Treg cells in tumors." (PMID 30744691, 2019). "The aim of this study was to determine the mechanism by which HMGB1 promotes tumor growth in DLBCL and whether blockade of HMGB1 signaling pathway could inhibit tumorigenesis." (PMID 30988279, 2019). "Functional experiments were carried out to check whether docetaxel (DOC), a chemotherapeutic agent, modifies the expression of HMGB1 and CXCL11, and influences the infiltration properties of CD8+ T cells to the tumor microenvironment." (PMID 30744691, 2019). "However, NETs can trigger HMGB1 (High mobility group box 1) release, activating TLR9-dependent pathways in cancer cells, thereby promoting tumor cell adhesion, proliferation, migration, and invasion after surgical stress." (PMID 31477121, 2019). "Heat shock-induced plasma membrane translocated CRT and released HMGB1 mediated an optimal antigen-presenting cell (APC) maturation and antigen cross-presentation, providing a unique strategy to obtain efficient tumor antigen-presenting cells with a mature DC-like phenotype." (PMID 31886313, 2019). "None of the tumor factors, including tumor diameter, tumor ulceration, histological type of adenocarcinoma, T state, and N stage, significantly correlated with HMGB1 expression level." (PMID 31399104, 2019). "To understand which molecules were responsible for this activity we performed experiments of THP1 activation with tumor cell supernatants in the presence of neutralizing Abs and BoxA to inhibit IL-1α, TNF-α, IL-18 and HMGB1, respectively, which are released by tumor cells." (PMID 30760333, 2019). "In a similar line, intracellular HMGB1 has also been shown to facilitate Peroxisome proliferator-activated receptor γ (PPARγ) coactivator 1α (PGC1α) expression and mitochondrial biogenesis in hypoxic HCC cells, hence promoting tumor survival and proliferation." (PMID 31731454, 2019). "For instance, it has been shown that by releasing pro-inflammatory mediators such as high mobility group box 1 (HMGB1), radiation-induced tumor cell necroptosis may boost anti-tumor immunity and improve prognosis." (PMID 31922095, 2019).
tumor (continued). "Like in the case of HMGB1, results of similar experiments showed that tumor growth in both flanks was markedly inhibited by the combination treatment of HSP70 injected to the right-side tumor and intravenously administered eMIP." (PMID 31058025, 2019). "In addition, the increased CRT exposure and enhanced HMGB1 release were also both confirmed by CRT staining of tumor tissue sections and western blot analysis of CRT and HMGB1 expressions." (PMID 30937276, 2019). "In addition to HMGB1, calreticulin (CRC) has also been shown to be expressed on the surface of cells following RT leading to better anti-tumor immunity." (PMID 30692991, 2018). "Heat shock-induced DAMPs, particularly plasma membrane translocated eCRT and released HMGB1, mediate an optimal antigen presenting cell (APC) maturation and antigen cross-presentation, providing a unique strategy to obtain efficient tumor antigen-presenting cells with a mature DC-like phenotype." (PMID 29600445, 2018). "HMGB1 secreted by ICD cells has been shown to stimulate cross-presentation by DCs of neoantigens from cancer cells and subsequently activate CD4 T cells that kill tumor cells and establish antitumor immunological memory." (PMID 29636841, 2018). "Taken together, we concluded that HMGB1 and HMGN1 secreted by cancer cells may relate to recruitment of tumor infiltrating lymphocytes (TILs) in HNSCC." (PMID 30619746, 2018). "In our study, HMGB1 was highly expressed on tumor-derived exosomes but not on hepatocyte-derived exosomes." (PMID 30526680, 2018). "In contrast, serum HMGB1 did not correlate with intracellular HMGB1 levels nor with human or mouse VEGF levels in the tumor tissues." (PMID 30123419, 2018). "The crucial roles of HMGB1 signaling in tumor development and the progression of various processes are now well established." (PMID 29651425, 2018). "Although the direct role of HMGB1 in stimulating tumor repopulation has not been described before, many studies have been published on other roles of HMGB1 in mammalian biology." (PMID 29844348, 2018). "The HMGB1 in non-irradiated and irradiated tumor cells was mainly localized in the nucleus, whereas in irradiated tumor cells, we found amount of multinucleate cells with altered nucleo-cytoplasmic ratio and nuclear atypic." (PMID 29844348, 2018). "The major source of HMGB1 in the cultures was the tumor-derived exosomal membrane, not the active or passive release of HMGB1 from B cells." (PMID 30526680, 2018). "In addition, HMGB1 silencing greatly affected the proliferative and tumorigenic potential of HPV-positive tumor cells." (PMID 29472602, 2018). "Indeed, HMGB1 regulates cancer metabolism by inducing mitochondrial complex I activity in a RAGE-dependent manner, leading to tumor cell proliferation and migration." (PMID 29636841, 2018). "Therefore, we used inhibitor of RAGE (FPS-ZM1) in tumor cell repopulation model and found that the repopulation was significantly suppressed, further proving that RAGE participated in HMGB1-mediated proliferating stimulation." (PMID 29844348, 2018). "The roles of HMGB1 probably are of crucial importance in HCC tumorigenesis and tumor development." (PMID 29651425, 2018). "For example, HMGB1 could activate the JAK/STAT pathway, decrease tumor cell apoptosis, promote cell cycle, and induce resistance and immune escape in tumor cells." (PMID 28968989, 2017). "CD24 and TIM‐3 are negative receptors that inhibit HMGB1 immune activity in macrophages, DCs and tumour cells." (PMID 28039939, 2017). "During hypoxia, HMGB1 translocates from nucleus to the cytosol, binds to mtDNA released from damaged mitochondria, and subsequently activates TLR9 signaling pathway to promote tumor cell proliferation." (PMID 28969092, 2017). "In particular, autophagy-deficient malignant cells fail to secrete ATP and to release high-mobility group box 1 (HMGB1) as they die, underlying their inability to trigger tumor-targeting immune responses in the absence of exogenous adjuvants." (PMID 27974686, 2017).
tumor (continued). "It suggested that highly expressed HMGB1 did not mediate the proliferation of tumor cells by directly inhibiting adaptive immune response." (PMID 28968989, 2017). "This study aimed to investigate whether miR-200c exerts tumour suppressor effects in NSCLC in vivo and in vitro via downregulating HMGB1 and thereby reducing EMT, invasion, and migration." (PMID 28727734, 2017). "The data showed that miR-200c was significantly downregulated in tumour tissue compared with normal tissue; in addition, the overexpression of HMGB1 did not directly affect miR-200c expression in NSCLC." (PMID 28727734, 2017). "Extracellular HMGB1 induces apoptosis in DCs, thus suppressing CD8+ T-cells function and enhancing Treg function and diminishing host anticancer immunity within the necrotic core, which lead to tumor progression." (PMID 27493669, 2016). "Further, HMGB1 inhibited the growth of HMGB1-sensitive SW480 xenograft tumours in nude mice, whereas treatment with a combination therapy of HMGB1 and L-DON substantially inhibited the growth of HMGB1-resistant HT29 xenograft tumours." (PMID 26948869, 2016). "Moreover, HMGB1 and HSP70/90 from immunogenic tumor cells interact with TLR4 on DCs, which activates the antigen processing and presentation machinery in DCs." (PMID 27240347, 2016). "Indeed, several studies showed that inhibiting HMGB1-RAGE or HMGB1-TLR4 interactions suppresses inflammation, tumor growth, and metastasis in animal models." (PMID 27493669, 2016). "Markers of immunogenic tumor cell death alone are not likely to be sufficient, insofar as HMGB1 release occurs in CPA-treated B16F10 tumors, which we found are largely immune unresponsive to CPA/6d treatment." (PMID 27515027, 2016). "Osteosarcoma tumor macrophages also produce high motility group box 1 (HMGB1), which interacts with the receptor for advanced glycation end products (RAGE), toll‐like receptors, and CD24, resulting in tumor proliferation, invasion and angiogenesis mediated by NFκB and VEGF signaling." (PMID 28536380, 2016). "They demonstrated that hyperacetylated HMGB1 was significantly higher in MM patients compared with asbestos-exposed individuals and healthy controls, and did not vary with tumor stage." (PMID 27171110, 2016). "In this context High Mobility Group Box-1 (HMGB1) may represent a link between NK cells and tumor cell progression." (PMID 27294158, 2016). "It is known that regulatory T cell-mediated/IL-10-dependent suppression of CD8+ T cells can be blocked by removal of tumour-derived HMGB150, which is consistent with our observation that HMGB1 inhibition leads to delayed tumour growth although via an alternate mechanism." (PMID 27426915, 2016). "Many studies suggested that HMGB1 interacts with RAGE mainly in tumor cells but not in normal tissues." (PMID 26499944, 2016). "In a previous report, we described the activation of MIA via interactions of intracellular HMGB1 with NFkBp65 and observed the strong implication of MIA in tumor progression and nodal metastasis through the induction of angiogenesis and lymphangiogenesis in OSCC." (PMID 27145272, 2016). "Our data suggest that, although HMGB1 clearly contributes to the accumulation of M2-like macrophages within tumours, it does not appear to be directly involved in M2 polarization." (PMID 27426915, 2016). "Noteworthy, tumour cells or tumour-infiltrating immune cells seem not to be the sole source of HMGB1." (PMID 27426915, 2016).
tumor (continued). "In contrast, nuclear HMGB1 localisation was predominantly observed in HIF-1α-negative areas of the tumour, and no evident co-labelling of anti-HMGB1 and HIF1α antibodies was observed in such areas." (PMID 27426915, 2016). "Finally, the recently highlighted role of HMGB1 both in EMT and in amplifying the recruitment of NK cells provides further hints on a possible effect of NK cells on tumor progression and fosters new studies on this issue." (PMID 27294158, 2016). "In PaCaDD135 tumor cells, increased phosphorylation of Erk was observed after treatment with almost all TLR ligands (ODN: 180%, LPS: 142%, HMGB1: 137%, ODN + HMGB1: 139%, and LPS + HMGB1: 170%) (left)." (PMID 27941651, 2016). "In addition, multivariate analyses indicated peritumoral HMGB1 expression, peritumoral TAM count, and tumor differentiation to be independent prognostic factors for RFS." (PMID 27836008, 2016). "Passively released HMGB-1 binds to receptors such as Toll-like receptor 4 (TLR4) with high affinity, and binding of HMGB-1 to TLR4 can activate NF-κB light chain, which play important roles in tumor growth and progression." (PMID 26872033, 2016). "HMGB1-RAGE interactions activate mitogen-activated protein kinase and protein kinase B signaling pathways, resulting in extracellular matrix degradation, tumor invasion and metastasis, leading to tumor development." (PMID 25574225, 2015). "Extracellular HMGB1 interacts with Toll-like receptors (TLRs) and receptor for advanced glycation end products (RAGE) on the DCs, which are involved selectively in the cross-priming of anti-tumor T lymphocytes in vivo." (PMID 26315113, 2015). "It is therefore not difficult to believe that HMGB1 acts as a proliferation factor that is involved in the dying-cell-stimulated proliferation of living tumor cells in this study." (PMID 25986235, 2015). "The results of the study indicate which redox form of extracellular HMGB1 mediates angiogenesis through VEGF-A, and HMGB1 in different redox states may be a novel therapeutic target for tumour angiogenesis." (PMID 26099505, 2015). "Similarly, other tumor-derived factors, such as gangliosides, mucin 2 (MUC2), and high-mobility group protein B1 (HMGB1), have been shown to trigger apoptosis of TADCs." (PMID 26690204, 2015). "In this study we analyzed the interactions between extracellular HMGB1 and the repressing action of the miRNAs 221/222 cluster on PTEN oncosuppressor mRNA that may lead to tumour progression." (PMID 26106610, 2015). "Given that recombinant HMGB1 can induce sCLU from tumor cells, we queried whether DTX could induce HMGB1 release." (PMID 26469759, 2015). "HMGB1 aids in the recruitment of endothelial precursor cells (EPC) using RAGE and TLR2/TLR4 in c-kit-positive EPC, thus, contributing to tissue repair and tumor growth." (PMID 24723911, 2014). "The interaction of HMGB1 with RAGE leads to activation of the NF-κB, MAPK, and type IV collagenase (MMP-2/MMP-9) signaling pathways, all of which degrade extracellular matrix protein and play a major role in tumor invasion and metastasis." (PMID 25356587, 2014). "In this study, we evaluate that whether HMGB1 can induce NF-κB activation through the interaction with RAGE and subsequently contribute to tumor invasiveness in HCC cells." (PMID 24510323, 2014). "Modification of HMGB1 localization has been shown to link autophagy and apoptosis, but the exact molecular mechanism of HMGB1-mediated autophagy in tumor therapy has not been clearly defined." (PMID 24996221, 2014). "However, a slight, but significant increased amount of extracellular HMGB1 was observed in T98G and U251MG tumor cells after fractionated RT, especially in combinations with VPA." (PMID 24678590, 2014). "Our study found that HMGB1 and HMGB2 were overexpressed in BCa tissues compared with normal tissues, and were correlated with both the clinical stage and pathological grade of the tumor." (PMID 23426143, 2013).